ALB (albumin)
Diseases named in the same sentence as ALB in open-access papers (continued):
Sharing a sentence is not in itself a finding about the gene and the disease.
hepatocellular carcinoma (continued). "Background and Aims: The Albumin-Bilirubin (ALBI) grade is a good index for liver function evaluation and is also associated with the outcomes of hepatocellular carcinoma patients receiving TACE." (PMID 35328217, 2022). "The scatter plot depicts positive association between HNF4a and the expression levels of ZO1 and ALB across 372 liver carcinoma samples from TCGA." (PMID 36132168, 2022). "The hepatocellular carcinoma cell line, HepG2, was cultured upon the scaffolds for 14 days and were analyzed through cell viability assay, DNA quantification, albumin quantification, immunohistochemistry, and RT‐qPCR gene expression analysis." (PMID 35734943, 2022). "We investigated the impact of C-reactive protein to albumin ratio (CAR) on predicting outcomes in 522 patients with unresectable hepatocellular carcinoma (HCC) treated with lenvatinib." (PMID 35589772, 2022). "The HepG2 human hepatic carcinoma cell line has been cultured upon the scaffolds and analyzed for cell viability, DNA quantitation, immunohistochemistry, albumin secretion and RT‐qPCR gene expression analysis of key hepatic functional and ECM markers." (PMID 35734943, 2022). "On the other hand, the application of A. cappadocicum extracts significantly reduced the albumin and urea release from the hepatocellular carcinoma cells." (PMID 35207423, 2022). "We developed and evaluated a modified albumin-bilirubin grade and α-fetoprotein (mALF) score, a nutritional and oncological assessment tool for patients with hepatocellular carcinoma (HCC) after surgical resection." (PMID 36358711, 2022). "ALB was experimentally shown to be a tumor suppressor in hepatocellular carcinomas, and has been discussed as an important part of the somatic mutation landscape." (PMID 33769711, 2021). "We elucidated usefulness of newly developed albumin–bilirubin (ALBI) score as alternative methods of BTR in patients with naïve hepatocellular carcinoma (HCC) retrospectively." (PMID 33960691, 2021). "This study was conducted to elucidate usefulness of newly developed albumin–bilirubin (ALBI) score as alternative methods of BTR for predicting amino acid imbalance that affects prognosis in naïve hepatocellular carcinoma (HCC) patients." (PMID 33960691, 2021). "The albumin-bilirubin (ALBI) score was initially validated to assess the outcome of patients with hepatocellular carcinoma (HCC), and its effectiveness has been confirmed by relevant studies." (PMID 34712321, 2021). "The PHMM analysis was performed to eliminate the impacts and effects of age, height, weight, baseline HBV DNA load, HBeAg status, ALT level, tumor size, proportion of sclerosing hepatocellular carcinoma, hemoglobin albumin level, and total bilirubin level." (PMID 34976330, 2021). "Similar to MTX, DOX was covalently conjugated with lactosaminated human albumin (L-HSA) to increase its efficacy in the treatment of hepatocellular carcinoma." (PMID 31858848, 2020). "Here we study the effect of albumin on HepG2/C3A hepatocellular carcinoma cell line, a contact inhibited subclone of the HepG2 cell line that retains some physiological functions of normal hepatocytes." (PMID 32185103, 2020). "ALB was demonstrated in previous literature to be a valuable prognostic and predictive factor in renal carcinoma, prostate cancer, hepatocellular carcinoma (HCC), and other various cancers." (PMID 32822383, 2020). "Accordingly, albumin-to-alkaline phosphatase ratio (AAPR) is postulated to be a prognostic indicator in hepatocellular carcinoma." (PMID 32517802, 2020). "Albumin-to-globulin ratio was related with the prognosis of hepatocellular carcinoma, small-cell lung cancer, and nasopharyngeal carcinoma." (PMID 32426277, 2020). "From these, a CRC model was developed, validated, and further compared with previously published prognostic models including four-and-seven criteria, six-and-twelve score, hepatoma arterial-embolization prognostic scores, and albumin-bilirubin grade." (PMID 32850345, 2020).
hepatocellular carcinoma (continued). "In recent studies, albumin has become a common indicator for predicting survival of a variety of cancers, such as osteosarcoma, renal cell carcinoma colorectal cancer, hepatocellular carcinoma, and prostate cancer." (PMID 33101044, 2020). "The more reliable imaging of variations in vascular properties at early times is consistent with previous findings that 68Ga-DOTA-albumin uptake revealed larger uptakes in highly angiogenic hepatomas than in the wild type tumors at 10–15 min." (PMID 32960353, 2020). "These primary findings demonstrate that albumin has immediate effects on HepG2/C3A hepatocellular carcinoma cells." (PMID 32185103, 2020). "Effects of albumin on hepatocellular carcinoma cell line have been previously studied demonstrating conflicting outcomes." (PMID 32185103, 2020). "Our results justify continued exploration into the strategy of using lactosylated albumin NPs as potential drug nanovehicles with selective direction toward the treatment of hepatocellular carcinoma." (PMID 30970533, 2019). "mRNAs of hepatocyte/hepatoma markers, such as albumin, ApoA1, CYP3A4, and AFP, were detectable in KH and Huh-7.5 cells, but not in A549 cells, indicating that KH cells, similar to Huh-7.5 cells, are derived from hepatocyte/hepatoma cells." (PMID 31138826, 2019). "We examined the mRNA expression levels of several hepatocyte/hepatoma markers, such as albumin, ApoA1, CYP3A4, HNF4α, OATP1B3, and AFP in both cell lines and in lung carcinoma-derived A549 cells by qRT-PCR." (PMID 31138826, 2019). "We aimed at determining the prognostic value of the albumin–bilirubin grade (ALBI) in patients undergoing transarterial Chemoembolization for unresectable Hepatocellular carcinoma." (PMID 31191834, 2019). "ZFNs targeting intron 1 of the human albumin locus were developed and used to insert hIDUA in the human hepatoma line HepG2." (PMID 30528089, 2019). "Recently, evidence has found that ALB was a useful prognostic predictor in various malignancies such as hepatocellular carcinoma (HCC), renal carcinoma, prostate cancer, and colorectal cancer as well as UTUC3,4,18–20." (PMID 30120312, 2018). "The ALBI grade calculated from albumin and bilirubin levels is considered to be a prognosis predictor like the Child-Pugh score in patients with hepatocellular carcinoma." (PMID 29108327, 2017). "Binding of HNF-1 to the promoter of albumin gene was decreased in hepatoma cells when they were incubated with 5% albumin, while hepatic albumin gene expression was suppressed in rats intravenously infused with albumin." (PMID 29295548, 2017). "With scoring systems excluded, history of hepatocellular carcinoma, mean arterial pressure (MAP), grade of hepatic encephalopathy, SpO2/FiO2, and serum level of bilirubin, albumin, and creatinine were independent risk factors for 6-week mortality." (PMID 28767684, 2017). "Bufalin-loaded bovine serum albumin nanoparticle is a promising liver-targeted drug delivery system with higher liver uptake and stronger antitumor activity against hepatocellular carcinoma." (PMID 28968991, 2017). "Recently, a novel technology using branched DNA-enhanced albumin RNA in situ hybridization was reported to distinguish hepatocellular carcinoma and ICA from metastatic PDAC." (PMID 27788482, 2016). "A 3D system for quantitative evaluation of the liver was used to fuse technetium-99m galactosyl human serum albumin single-photon emission computed tomography and computed tomography images from 20 patients with cirrhotic liver and hepatocellular carcinoma." (PMID 26945357, 2016). "Diacylglycerol acyltransferase‐1‐silenced hepatoma cell lines lost their hepatocyte‐specific functions, including albumin secretion, and well‐differentiated epithelial characteristics." (PMID 26493024, 2016). "In vivo AFP is only expressed during liver embryogenesis, in fetal liver cells, and hepatocellular carcinomas, while albumin is produced by differentiated hepatocytes in the adult liver." (PMID 27610270, 2016).
hepatocellular carcinoma (continued). "In the case in which hepatoma cells were exposed to NG, albumin secretion was lower by the same values in C3A and C3A-EGFP cells when compared to the control." (PMID 25816103, 2015). "Albumin, the typical protein synthesized by hepatocytes, serves as a popular indicator of changes in hepatoma cell physiology." (PMID 25816103, 2015). "The retention of albumin in tumors has since been observed in various experimental solid tumors (e.g., sarcoma, ovarian carcinoma, Novikof hepatoma, etc.)using radiolabeled- or dye-complexed serum albumin." (PMID 25161624, 2014). "Although albumin expression varies among different hepatocarcinoma types, high expression levels of this protein are generally observed in well-differentiated hepatocellular carcinomas." (PMID 24416255, 2014). "It has been described that extracellular stimuli like HGF are involved in the regulation of cell proliferation in hepatocellular carcinoma, as well as in the expression of albumin and alpha-fetoprotein." (PMID 24416255, 2014). "We first compared the kinetics of intra-Golgi transport of albumin with those of VSVG and PC-I in HepG2 cells, a human hepatoma cell line that secretes both albumin and antitrypsin." (PMID 24867214, 2014). "Low levels of albumin have been reported in the serum of patients and animals with hepatocellular cancer." (PMID 25136360, 2014). "Commitment of mouse hepatoma cells to increased albumin secretion was temporally dependent, requiring a minimum of 48 h in the presence of DMSO." (PMID 6194807, 1983). "Regarding PFI, higher DBF4B expression was associated with worse prognosis in subgroups such as Age > 60, BMI ≤ 25, Race: Asian, Gender: male, Residual tumor: R0, Histological type: Hepatocellular carcinoma, Tumor state: With tumor, Vascular invasion: Yes Albumin (g/dl): >= 3.5." (PMID 40535802, 2025). "In this respect, we should mention the fact that the studies published so far have demonstrated that the CRP/albumin ratio represents an important parameter in order to predict the long-term outcomes in other malignancies, such as hepatocellular carcinoma, esophageal or gastric carcinoma." (PMID 39061143, 2024). "It is noteworthy that some hepatocellular carcinomas resume expression of foetal albumin (alpha-fetoprotein, AFP), which may represent the reversion of some cancers towards a foetal hepatic state." (PMID 38195504, 2024). "The systemic immune-inflammation index–albumin-bilirubin score could be a simple indicator to estimate the prognosis in individuals with hepatocellular carcinoma being treated with transarterial chemoembolization." (PMID 36620927, 2023). "Another study showed that growing placenta MSCs on a 3D fluidized bioreactor and treating them with hepatoma-derived C3A significantly improved ALB, urea secretion, and increased CYP1A2 and CYP3A4 that indicated significant differentiation of SCs into hepatocytes." (PMID 36685673, 2023). "Studies have shown that ALB level, as an indicator of systemic inflammatory response, was helpful in judging the prognosis of solid tumors such as non-small cell lung cancer and hepatocellular carcinoma." (PMID 37875880, 2023). "In addition, it was reported that GPC3-GC was partially similar to hepatocellular carcinoma histologically, and functionally expressed albumin mRNA." (PMID 35050429, 2022). "To demonstrate loosely albumin-bound copper toxicity, we tested hepatic HepG2 cells (human hepatocellular carcinoma) and surrogate brain cell types, such as EA.hy926 (human endothelium), U87MG (human astrocytoma) and SHSY5Y (human neuroblastoma) cells for their vulnerability against Cu–albumin." (PMID 34857647, 2022). "Interestingly, as a combined ratio index derived from LFT, albumin to alkaline phosphatase ratio (AAPR) was firstly investigated to be a novel index of prognosis in hepatocellular carcinoma (HCC) patients in 2015." (PMID 33685425, 2021).
hepatocellular carcinoma (continued). "It has been reported by using in situ hybridization test that endogenous albumin mRNA may serve as a sensitive marker for detecting primary hepatic carcinoma." (PMID 34603055, 2021). "The compounds have a high capacity to bind serum albumin, exhibit the ability to inhibit the activities of α-amylase and intracellular PTPs, and furthermore, improve the phosphorylation of the insulin receptor in the human hepatoma (HepG2) cell line." (PMID 34067862, 2021). "The ALBI score, derived from a patient’s albumin and total bilirubin, was originally developed in patients with hepatocellular carcinoma for the reliable assessment of liver function, and an ALBI score of >−2.60 was proposed as a prognostic indicator for mortality." (PMID 34830658, 2021). "Additionally, higher cleavage activity of sRGN3.1 and sRGN3.3 compared to SpyCas9 was observed on the albumin locus in a murine hepatoma cell line." (PMID 34244505, 2021). "Thus, a combination of albumin-bilirubin grade and alpha-fetoprotein level can be used to stratify patients with unresectable hepatocellular carcinoma by progression-free survival and overall survival probability for sorafenib–regorafenib sequential therapy." (PMID 34359658, 2021). "Moreover, ALB has been found to suppress the cell cycle and progression of hepatocellular carcinoma." (PMID 32517802, 2020). "Although these cells secrete albumin, due to being hepatoma derived, they show characteristics of dedifferentiation from mature hepatocytes: Huh7 cells express tumor markers and have limited expression of CYP enzymes, hepatic transcription factors, and nuclear receptors." (PMID 32643289, 2020). "We observed hypoxia-induced DENV replication in human hepatoma cells as well as in a human hepatocyte cell line retaining important features of normal hepatocytes, including the secretion of liver-specific plasma proteins (albumin, fibrinogen, apoB)." (PMID 30513781, 2018). "The CRP/ALB ratio was also applied to predicting the prognosis of patients with cancer and its usefulness has been reported in patients with various cancers, such as hepatocellular carcinoma, esophageal cancer and lung cancer." (PMID 27812440, 2016). "A study on patients with pancreatic cancer showed that serum TNF-α levels were inversely correlated with BMI, hematocrit, hemoglobin, serum protein and albumin levels and similar observations were made in patients with prostate cancer and hepatocellular carcinoma." (PMID 26856534, 2016). "Furthermore, we studied the potential effects of AhR on the phenotype of the mouse hepatoma cells, including cell cycle, morphology and the expression of albumin." (PMID 19936078, 2007). "The albumin in liver and hepatoma had a higher mobility than that in plasma." (PMID 4340062, 1972). "Moreover, hepatocellular carcinoma patients with modified albumin-bilirubin grade 1 or 2a, together with platelets > 150,000/μL, may be able to avoid oesophagogastroduodenoscopy." (PMID 40674357, 2025). "This study aimed to investigate the association between a new biomarker that incorporates albumin (Alb) and butyrylcholinesterase (BCHE) levels, as well as the prognosis of hepatocellular carcinoma (HCC) after hepatectomy." (PMID 39658717, 2025). "In contrast, the ALBI score was specifically designed to classify hepatocellular carcinoma (HCC) patients, particularly those within Child–Pugh class A, based solely on albumin and bilirubin levels." (PMID 40277757, 2025). "The Fibrinogen-to-Albumin Ratio has emerged as a potential risk predictor for patients with bladder cancer, oral cancer, gastrointestinal mesenchymal tumors, gastric cancer undergoing chemotherapy, IB-IIA cervical cancer, hepatocellular carcinoma, gallbladder cancer, and pancreatic cancer." (PMID 38500655, 2024).
hepatocellular carcinoma (continued). "HepG-2 is a hepatoma cell line widely used to study liver function and hepatoxicity, mostly because they retain several features of differentiated hepatocytes, including insulin-stimulated glycogen synthesis, glutathione-based detoxification and albumin secretion." (PMID 38136171, 2023). "This study assessed the use of pretreatment albumin–-bilirubin (ALBI) grade as a prognostic factor in patients with hepatocellular carcinoma (HCC) receiving combined transarterial chemoembolization (TACE) and radiotherapy (RT)." (PMID 36836588, 2023). "Albumin-bilirubin (ALBI) grade is an objective measure of liver function for patients with hepatocellular carcinoma (HCC)." (PMID 34621044, 2022). "This study aimed to evaluate the clinical significance of the preoperative aminotransferase to albumin ratio (AAR) in patients with hepatocellular carcinoma (HCC) after hepatectomy." (PMID 35945520, 2022). "Moreover, the metabolic reprogramming via mutation or downregulation of hypermethylated genes, including apoB and albumin, was observed in hepatocellular carcinoma, which indicated that this genetic pattern of metabolism-related regulation was possible to promote the progression in malignant tumors." (PMID 36713523, 2022). "The albumin–bilirubin (ALBI) grade has been validated as a significant prognostic predictor for hepatocellular carcinoma (HCC)." (PMID 34666694, 2021). "Moreover, the association between albumin level and cancer has been extensively studied, in which a series of studies have found that albumin acts as a prognostic factor and can predict clinical outcomes of hepatocellular carcinoma, prostate cancer, acute myeloblastic leukemia, and GC." (PMID 34239566, 2021). "We investigated the impact on survival of modified albumin–bilirubin (mALBI) grade versus Child–Pugh classification in patients with hepatocellular carcinoma (HCC) who received lenvatinib." (PMID 34262065, 2021). "The present study was conducted to elucidate usefulness of newly developed albumin–bilirubin (ALBI) score as alternative methods of BTR for predicting amino acid imbalance that affects prognosis in naïve hepatocellular carcinoma (HCC) patients." (PMID 33960691, 2021). "The novel CRP–albumin–lymphocyte (CALLY) index has been identified as a highly predictive tool for stratification of patients with hepatocellular carcinoma (HCC) who have undergone tumor resection." (PMID 34638502, 2021). "The albumin-bilirubin (ALBI) grade has been validated as a significant predictor for hepatocellular carcinoma (HCC)." (PMID 32350365, 2020). "Recently, the albumin-to-alkaline phosphate ratio (AAPR), a novel prognostic factor, has been demonstrated to be significantly associated with poorer urologic outcomes for hepatocellular carcinoma (HCC), metastatic nasopharyngeal carcinoma, and upper tract urothelial carcinoma (UTUC) 13-17." (PMID 31632493, 2019). "The PNI, which combines serum albumin and the lymphocyte count has been demonstrated as a prognostic factor in several malignant tumors, including colorectal cancer, gastric cancer, malignant pleural mesothelioma, hepatocellular carcinoma, pancreatic cancer and small cell lung cancer." (PMID 27399281, 2016). "In epidemiological studies, PAH–albumin and PAH–DNA adducts, which reflect PAH exposure, are associated with an elevated risk of hepatocellular carcinoma (HCC)." (PMID 25325763, 2015). "Here, the utility of an albumin-indocyanine green-based China liver cancer (CNLC) staging system (ALICE-CNLC) as a tool for the prognostic assessment of hepatocellular carcinoma (HCC) patients was evaluated, comparing this system to the Child-Pugh score-based CNLC staging system." (PMID 40052123, 2025). "In recent years, the albumin-to-bilirubin (ALBI) score, which consists of only two serum parameters, has been introduced as a prognostic indicator for hepatocellular carcinoma (HCC) and has proven useful in stratifying patients within CP class A." (PMID 40277757, 2025).